FOXO6 (forkhead box O6)
Description:
Transcriptional activator.
Tractability: PROTAC: ubiquitination databases record sites on it.
Gene: Protein-coding gene on chromosome 1 (41,361,922 to 41,383,590, forward strand). Ensembl gene ENSG00000204060.
Subcellular location: Cytoplasm; Nucleus
Pathways (Reactome):
Gene expression (Transcription): FOXO-mediated transcription of oxidative stress, metabolic and neuronal genes; Regulation of localization of FOXO transcription factors
Disease: Constitutive Signaling by AKT1 E17K in Cancer
Signal Transduction: AKT phosphorylates targets in the nucleus
Gene Ontology:
Molecular function: protein binding; DNA-binding transcription factor activity, RNA polymerase II-specific; RNA polymerase II cis-regulatory region sequence-specific DNA binding; beta-catenin binding; DNA-binding transcription activator activity, RNA polymerase II-specific; DNA-binding transcription factor activity; sequence-specific DNA binding
Biological process: positive regulation of dendritic spine development; regulation of transcription by RNA polymerase II; memory; positive regulation of transcription by RNA polymerase II; regulation of DNA-templated transcription
Cellular component: chromatin; cytoplasm; nucleus
Genetic constraint (gnomAD): Loss-of-function variants: 8 observed, 13.14 expected, observed/expected ratio (o/e) 0.61, 90% interval 0.36 to 1.1. The synonymous counts are far from expectation, so gnomAD's model fits this gene poorly and the ratio says little. Missense variants: 518 observed, 441.88 expected, observed/expected ratio (o/e) 1.17, 90% interval 1.09 to 1.26. Synonymous variants: 279 observed, 209.86 expected, observed/expected ratio (o/e) 1.33, 90% interval 1.21 to 1.47.
Homologues: Orthologues: chimpanzee FOXO6 (99% identical), macaque FOXO6 (99% identical), dog FOXO6 (97% identical), rat Foxo6 (97% identical), mouse Foxo6 (96% identical), pig FOXO6 (90% identical), guinea pig FOXO6 (84% identical), tropical clawed frog foxo6 (53% identical), zebrafish foxo3b (45% identical), zebrafish foxo3a (44% identical). Paralogues in human: FOXO3 (43% identical), FOXO1 (39% identical), FOXO4 (37% identical), FOXC1 (15% identical), FOXK1 (15% identical), FOXM1 (15% identical), FOXK2 (15% identical), FOXD3 (14% identical), FOXD4 (14% identical), FOXJ2 (14% identical), FOXA1 (14% identical), FOXC2 (14% identical), and 29 more.
Diseases named in the same sentence as FOXO6 in open-access papers:
FOXO6 is named in the same sentence as 44 diseases in open-access papers, as found by Europe PMC text mining. Sharing a sentence is not in itself a finding about the gene and the disease. The quoted sentences say what the papers report.
gastric cancer (9 papers, 2016 to 2025). A primary or metastatic malignant neoplasm involving the stomach. "FOXO6 overexpression is associated with poor prognosis in patients with gastric cancer and is observed in patients with serosal infiltration and lymph node metastasis." (PMID 34123834, 2021). "Our data revealed that FOXO6 was significantly associated with MMP-9 expression in 192 gastric cancer samples (r = 0.503, P < 0.001)." (PMID 28404958, 2017). "Our datas found that FOXO6 was positively associated with the expression of MMP-9 in gastric cancer." (PMID 28404958, 2017). "FOXO6 expression could be used to identify high-risk factors of gastric cancer patients, which will help to select appropriate therapies." (PMID 28404958, 2017). "Therefore, it suggests that FOXO6 could be a potential prognostic biomarker for different risk of gastric cancer patients." (PMID 28404958, 2017). "LncRNA NORAD promotes gastric cancer cell proliferation by regulating miR-608 and affecting FOXO6 protein expression." (PMID 38698487, 2024). "In contrast, FOXO6 promotes gastric cancer cell proliferation through cMyc induction, and its loss inhibits colorectal cancer cell proliferation, invasion and glycolysis, with decreased PI3K/AKT/mTOR pathway activation." (PMID 39499086, 2024). "The lncRNA NORAD has also been found to bind to miR-608 in cancer and upregulate forkhead box O6 (FOXO6) in gastric cancer, accelerating cell growth." (PMID 35387124, 2022). "NORAD promotes gastric cancer cell proliferation and migration by regulating the miR-608/FOXO6 pathway." (PMID 32267831, 2020). "In conclusion, this study established a correlation between FOXO6 expression and gastric cancer prognosis." (PMID 28404958, 2017). "To verify the functions of FOXO6 in gastric cancer, we correlated FOXO6 expression with other widely recognized clinicopathologic features." (PMID 28404958, 2017). "The FOXO6 correlated with tumor progression in a wide range of carcinomas, yet little is known in gastric cancer." (PMID 28404958, 2017). "High FOXO6 expression was found in 98 of the 192 (51.0%) gastric cancer samples, compared with 31/176 (17.6%) in para-carcinoma tissues (P < 0.001)." (PMID 28404958, 2017). "We firstly detected FOXO6 expression in 192 gastric cancer specimens, as compared with the levels in matched adjacent non-tumorous gastric tissues." (PMID 28404958, 2017). "Our datas showed that FOXO6 expression in gastric cancer samples was higher, compared with para-carcinoma tissues." (PMID 28404958, 2017). "Our data revealed that FOXO6 overexpression was a negatively independent predictor for OS in patients with gastric cancer (HR = 3.275, 95% CI: 2.201-4.873; P < 0.001)." (PMID 28404958, 2017). "In this study, FOXO6 expression was detected in 192 gastric cancer samples using immunohistochemistry." (PMID 28404958, 2017). "Overexpression of FOXO6 was positively related to depth of invasion, lymph node metastasis and stage of disease in gastric cancer (all P < 0.001)." (PMID 28404958, 2017). "We evaluated the relationship of FOXO6 expression with depth of invasion and lymph node metastasis in gastric cancer." (PMID 28404958, 2017). "A definite FOXO6 inhibitor is not yet characterized but in silico studies have demonstrated the porfimer sodium to be a potential FOXO6 inhibitor that may suppress gastric cancer progression (Poleboyinaet al., 2023)." (PMID 40260403, 2025). "However, some studies have demonstrated that FOXO6 serves important roles in the occurrence and development of gastric cancer, lung cancer, and HCC." (PMID 34123834, 2021). "In conclusion, FOXO6 overexpression promotes tumor aggressiveness and prognosis, and could be a promising target for prognostic prediction in gastric cancer patients." (PMID 28404958, 2017). "However, further studies are required to illuminate the potential biological function of FOXO6 in gastric cancer." (PMID 28404958, 2017).
gastric cancer (continued). "In addition, FOXO6 expression was positively correlated with MMP-9 among 192 gastric cancer tissues." (PMID 28404958, 2017). "The expression of FOXO6 was mainly in the nucleus of gastric cancer cells." (PMID 28404958, 2017). "Therefore, the purpose of this study is to investigate the correlation of FOXO6 expression with clinicopathological features and prognosis in gastric cancer." (PMID 28404958, 2017). "Our results suggested that FOXO6 was overexpression in gastric cancer tissues." (PMID 28404958, 2017). "Moreover, the median times of OS and RFS in FOXO6 over-expression (n = 98) gastric cancer patients were 15.0 months and 9.5 months, which were significantly shorter than those with FOXO6 low-expression (n = 94) (36.0 months and 39.0 months)." (PMID 28404958, 2017). "Our results and previous findings powerfully suggest that FOXO6 overexpression may promote tumor progression, and work as an independent predictor for gastric cancer patients." (PMID 28404958, 2017). "The aim of this study was to analyze the role of FOXO6 in patients with gastric carcinoma." (PMID 28404958, 2017). "FOXO6 could be a promising predictor for prognosis in gastric cancer." (PMID 28404958, 2017). "Our finding concluded that FOXO6 could serve as a feasible prognostic biomarker of gastric cancer." (PMID 28404958, 2017). "Moreover, previous datas revealed that the FOXO6 could regulate the synaptic function and hepatic glucose homeostasis in mice, and promote oncogenicity of gastric cancer via upregulation of C-myc signal pathway." (PMID 28404958, 2017). "However, the prognosis of FOXO6 gene in gastric cancer remains unknown." (PMID 28404958, 2017). "The correlation between FOXO6 expression with MMP-9, clinicopathological/prognostic value in gastric cancer was examined." (PMID 28404958, 2017). "The relationship of FOXO6 and MMP-9 expression was verified by IHC methods in serial sections of gastric cancer samples." (PMID 28404958, 2017). "However, the prognostic significance of FOXO6 expression in gastric cancer is still unknown." (PMID 28404958, 2017). "According to the results of multivariate analysis, FOXO6 overexpression was an independent indicator for poor OS and RFS in gastric cancer patients." (PMID 28404958, 2017). "The expression of FOXO6 and matrix metallopeptidase 9 (MMP-9) was assessed by immunohistochemistry in 192 gastric carcinoma specimens." (PMID 28404958, 2017). "Moreover, to confirm the value of FOXO6 expression on survival (OS and RFS) in patients with gastric cancer, we analyzed the correlation between clinicopathologic parameters and patients outcomes by univariate analysis." (PMID 28404958, 2017). "Moreover, FOXO6 expression was positively correlated with depth of invasion, lymph node metastasis and TNM stage in gastric cancer." (PMID 28404958, 2017). "In addition, FOXO6 overexpression was an important factor of poor prognosis in gastric cancer patients that independent of tumor invasion." (PMID 28404958, 2017). "Therefore, the correlation of FOXO6 and MMP-9 expression was evaluated in gastric cancer patients." (PMID 28404958, 2017). "Therefore, FOXO6 could be a potential prognostic indicator for gastric cancer patients that independent of tumor invasion." (PMID 28404958, 2017). "Furthermore, the prognostic significance of FOXO6 in different risk of subgroups based on tumor size, depth of invasion and lymph node metastasis was assessed, which appeared that FOXO6 could be a negative prognostic biomarker for different risks of gastric cancer patients." (PMID 28404958, 2017).
breast carcinoma (7 papers, 2018 to 2025). "Upregulated genes included FoxO6 in endothelial cells, a transcription factor with limited evidence linking it to breast cancer, and Hs3st6, encoding an enzyme involved in heparan sulfate biosynthesis, a pathway known to influence tumour cell proliferation." (PMID 40925719, 2025). "FOXO6 overexpression is therefore associated with low activity of the PI3K/AKT pathway in breast cancers." (PMID 29484124, 2018). "PAK1 is upregulated in various cancer types, integrates various signalling pathways, such as PI3K and RAS, and has been reported to phosphorylate and inactivate FOXO1 in breast cancer and FOXO6 in liver ageing." (PMID 39499086, 2024). "The least mentioned member of the FOXO family in relation to cancer FOXO6 is downregulated in breast cancer tissue compared to adjacent normal tissue, and also in breast cancer cell lines compared to the non-tumorigenic breast epithelial cell line MCF10A." (PMID 38136293, 2023). "The overexpression of FOXO6 has previously been demonstrated to inhibit the migration and invasion of breast cancer cells." (PMID 36555288, 2022). "Another study demonstrated that overexpression of forkhead box O6 inhibits the migration and progression of breast cancer cells." (PMID 34285764, 2021). "They suggested that upregulation of FOXO6 was shown to inhibit epithelial-mesenchymal transition and migration of breast cancer cells and vice versa." (PMID 34285764, 2021). "Altogether, these results indicate that, among the four members of the FOXO gene family, only FOXO6 is overexpressed in breast cancer." (PMID 29484124, 2018). "Other studies are required to more clearly define the molecular mechanisms responsible for FOXO6 overexpression in breast cancer." (PMID 29484124, 2018). "Similarly, the overexpression of FOXO6 inhibits the invasiveness and migration of breast cancer cells." (PMID 36555288, 2022). "The PI3K-AKT pathway has been shown to inhibit FOXO1, 3 and 4 expression, suggesting that FOXO6 overexpression in breast cancers could be due to impaired activity of this pathway." (PMID 29484124, 2018). "However, the reason why FOXO6 plays a different role in breast cancer compared to the other FOXO members has yet to be elucidated." (PMID 29484124, 2018). "Our results therefore strongly suggest that FOXO6 might be an oncogene in human breast cancer, which positively regulates cell proliferation by activating the progression of cancer cells through the G0/G1 phase." (PMID 29484124, 2018). "We therefore investigated if FOXO6 overexpression could be a prognostic marker in a subpopulation of breast cancer." (PMID 29484124, 2018). "FOXO6, which is intensely expressed in breast cancers, but expressed at very low levels in normal adult tissues, may therefore be a potential candidate as a target for breast cancer therapy." (PMID 29484124, 2018). "To further investigate the possibility that FOXO6 might modulate the proliferation of breast cancer cells, we examined the effect of inhibiting the expression of endogenous FOXO6 on proliferation of the breast cell line MDA-MB-468 expressing high levels of this FOXO gene." (PMID 29484124, 2018). "Therefore, FOXO6 would play an important role in carcinogenesis, notably in breast cancer." (PMID 29484124, 2018). "In contrast with FOXO1, FOXO3, and FOXO4, FOXO6 could therefore be an oncogene in breast cancer." (PMID 29484124, 2018). "The molecular mechanisms responsible for altered FOXO6 expression in breast cancer are unknown." (PMID 29484124, 2018). "The high expression of FOXO6 was not a marker of poor prognostic in HR- ERBB2+, HR+ ERBB2-, HR+ ERBB2+, lobular, or ductal breast cancer." (PMID 29484124, 2018). "Western blot analysis demonstrated FOXO6 protein expression in breast cell lines expressing a high level of FOXO6 mRNA, but not in breast cell lines expressing low levels of this mRNA or in the normal mammary cell line MCF10A, confirming FOXO6 protein overexpression in breast cancer cells." (PMID 29484124, 2018).
colorectal cancer (5 papers, 2021 to 2024). A primary or metastatic malignant neoplasm that affects the colon or rectum. "The research indicated that FOXO6 knockdown inhibited cell proliferation, migration, invasion and glycolysis of colorectal cancer cells by inhibiting the PI3K/AKT/mTOR signaling pathway." (PMID 37822879, 2023). "Knockdown of FOXO6 in colorectal cancer cells inhibited the cell proliferation, migration, invasion and glycolysis." (PMID 35189817, 2022). "FOXO6 has distinct subcellular shuttling dynamics and a more restricted expression pattern than other FOXOs and contributes to the pathogenesis of several types of tumors, including breast and colorectal cancer." (PMID 37011861, 2023). "Additionally, overexpression of FOXO6 can inhibit tumor cell invasion and migration in colorectal cancer." (PMID 34123834, 2021). "Additionally, Li’s research found that knockdown of FOXO6 could inhibit the phosphorylation of PI3K, AKT and mTOR (p < 0.01), and decrease the expressions of P-PI3K, P-AKT and P-mTOR in colorectal cancer cells." (PMID 37822879, 2023).
hepatocellular carcinoma (5 papers, 2016 to 2025). A malignant tumor that arises from hepatocytes. "The aim of this study was to explore the association of Forkhead box O6 (FOXO6) expression with oxidative stress level and prognosis of hepatocellular cancer (HCC)." (PMID 27227932, 2016). "FOXO6 promotes inflammation by activating cytokine IL-1β and induces lipid triglyceride accumulation in the mouse liver and human hepatocellular carcinomas." (PMID 38835896, 2024).
lung carcinoma (5 papers, 2015 to 2022). "Thus, in addition to EGFR-FOXO6-SOX2 feedback loop, the expression of FOXO6 can also be regulated by FOXO6-eRNA, which provided novel implications for the targeted therapy of FOXO6-related erlotinib resistance in lung cancer patients." (PMID 33042282, 2020). "FOXO6 therefore behaves like a tumour suppressor gene in lung cancer." (PMID 29484124, 2018). "Moreover, FOXO6 overexpression inhibits the proliferation of A549 human lung cancer cells, whereas knockdown of endogenous FOXO6 expression enhances cell proliferation." (PMID 29484124, 2018). "However, FOXO6 has also been shown to be downregulated in lung cancer compared to adjacent normal tissue." (PMID 29484124, 2018).
diabetes (3 papers, 2016 to 2021). "The dearth of differences between wild-type and Foxo-deficient ALDH+ cells is wholly consistent with the concept that in diabetes there is a ‘spontaneous' loss of Foxo6, 7, 8, and that Foxo normally restrains ALDH1A3 expression." (PMID 27572106, 2016). "Forkhead box class O6 (FOXO6) is a member of the FOXO family that can regulate diabetes-induced OS, and the suppression of FOXO6 protects ARPE-19 cells from HG-induced OS and apoptosis, which is in part mediated by the activation of the Akt/Nrf2 pathway." (PMID 32273949, 2020). "Induction of diabetes also leads to decreased expression levels of the transcription factor FOXO6." (PMID 33744871, 2021).
Insulin resistance (3 papers, 2021 to 2024). Increased resistance towards insulin, that is, diminished effectiveness of insulin in reducing blood glucose levels. "In our study, we uncovered the involvement of gluconeogenesis and FoxO6 in the context of insulin resistance." (PMID 38441531, 2024). "Our previous study confirmed that FoxO6-mediated IL-1β is involved in hepatic inflammation and insulin resistance via TF/PAR2/Akt pathway in aging and diabetic liver." (PMID 34631216, 2021). "Based on these findings, we proposed the hypothesis that hyperglycemia-mediated FoxO6 plays a pivotal role in hindering insulin signaling, subsequently prompting the induction of gluconeogenesis-related genes in conditions marked by insulin resistance." (PMID 38441531, 2024).
lung adenocarcinoma (3 papers, 2018 to 2022). A carcinoma that arises from the lung and is characterized by the presence of malignant glandular epithelial cells. "Another interesting finding was the identification of FOXO6 as a novel driver gene for lung adenocarcinoma." (PMID 33042282, 2020). "Further qPCR also revealed that the expression of one FOXO6-eRNA was significantly higher in PC9 cell line (EGFR mut-type) than that in other two EGFR wide-type lung adenocarcinoma cell lines (A549 and NCI-H1299)." (PMID 33042282, 2020). "By integrating the copy number information, we identified that four of above defined 129 upregulated eRNAs targeting FOXO6, TERT and PAX9 were activated by CNA in lung adenocarcinoma samples." (PMID 33042282, 2020). "FOXO6 expression was upregulated in lung adenocarcinoma, which was predominantly attributed by the CNA of FOXO6-eRNA." (PMID 33042282, 2020).